BST1 (bone marrow stromal cell antigen 1)
Diseases named in the same sentence as BST1 in open-access papers (continued):
Sharing a sentence is not in itself a finding about the gene and the disease.
endometrial cancer (1 paper, 2024). Primary or metastatic malignant neoplasm involving the endometrium (mucous membrane that lines the endometrial cavity). "We confirmed by qRT-PCR that the mRNA expression levels of APOE, BGN, BST1, and C1QB in endometrial cancer cell lines (HEC-1B and Ishikawa) were consistent with our previous results." (PMID 39650066, 2024). "In our qRT - PCR verification, the expressions of APOE, BGN, BST1, and C1QB in endometrial cancer cell lines were different from those in normal endometrial epithelial cells, which was consistent with our analysis." (PMID 39650066, 2024). "Among them, APOE, BGN, BST1, and BGN showed expression differences in endometrial cancer." (PMID 39650066, 2024). "The mRNA expression levels of APOE, BST1, and C1QB in endometrial cancer cell lines were significantly higher than those in normal endometrial epithelial cells, whereas BGN expression was higher in normal endometrial cell lines than in endometrial cancer cell lines." (PMID 39650066, 2024). "The four hub genes (APOE, BST1, BGN, C1QB) with differential expression in endometrial cancer tissues may serve as potential therapeutic targets, warranting further research to validate their effectiveness as potential prognostic markers and treatment targets for endometrial cancer." (PMID 39650066, 2024).
ependymoma (1 paper, 2024). A WHO grade II, slow growing tumor of children and young adults, usually located intraventricularly. "BST1, FLG, KANK4, and SHISA9 were significantly higher expressed in SP-EPN subtype A compared to all other ependymomas, whereas AK5, CFTR, RASSF6, and TBX22 showed high expression in subtype B." (PMID 38265489, 2024).
inflammatory bowel disease (1 paper, 2021). A spectrum of small and large bowel inflammatory diseases of unknown etiology. "In particular, BST1 is abundant in the intestine, and inflammatory bowel diseases are also mediated in part by macrophages." (PMID 34799586, 2021).
male infertility (1 paper, 2023). The inability of the male to effect fertilization of an ovum after a specified period of unprotected intercourse. "Single-cell RNA sequencing (scRNA-seq) was performed on various types of germ cells at the spermatogenic stage as a way to assess intercellular variability and to reveal some bridge genes in spermatogenesis, such as DNA JC5B, BST1, and PTMs, which have been shown to play a role in male infertility." (PMID 38133353, 2023).
Nephropathy (1 paper, 2022). A nonspecific term referring to disease or damage of the kidneys. "Furthermore, there is a report that blocking Sphk2, which is highly expressed in the proximal tubules, improved cisplatin-induced nephropathy, suggesting that Bst1 may be related to other factors besides fibrosis." (PMID 36267620, 2022).
ovarian tumours (1 paper, 2016). "Consistent with BST1's potential role in cancer, it is overexpressed in ovarian tumours and is correlated with shorter survival." (PMID 26806015, 2016).
renal fibrosis (1 paper, 2022). A final common manifestation of a wide variety of chronic kidney diseases characterized by glomerulosclerosis and tubulointerstitial fibrosis. "In summary, we have identified Bst1 as a downstream target of Sphk2 that has a previously unrecognized role in kidney injury and revealed that Bst1 deficiency leads to less renal fibrosis." (PMID 36267620, 2022). "Bst1 research in the kidney has just begun and further research is needed on the localization of Bst1 in the kidney and the molecular mechanism of how Bst1 causes renal fibrosis." (PMID 36267620, 2022). "We revealed that Bst1 is critical in the development of renal fibrosis." (PMID 36267620, 2022). "Bst1/CD157 was identified as a gene that is regulated by SphK2 through a change in histone acetylation level, and Bst1–/– mice were found to develop less renal fibrosis after unilateral ischemia-reperfusion injury, a mouse model of kidney fibrosis." (PMID 36267620, 2022). "To evaluate the role of Bst1 in the context of fibrosis, we subjected Bst1–/– mice to unilateral IRI, the same method applied to Sphk2–/– mice, and found that Bst1–/– mice developed less renal fibrosis than WT controls." (PMID 36267620, 2022).
synovitis (1 paper, 2022). Inflammation of a synovial membrane. "We suggest that BST1 might be communicating with specific cell types in OA synovitis by cell communication." (PMID 35720295, 2022). "While the data used in the analysis were not representative of BST1 gene expression in specific cell types of OA synovitis, the single-cell sequencing may help us to understand the role of SCRG1 in cell communication." (PMID 35720295, 2022).
systemic candidiasis (1 paper, 2016). "Moreover, BST1 null mutants or those expressing Bst1 variants did not display inositol deacylation activity and exhibited severely attenuated virulence and reduced organic colonization in a murine systemic candidiasis model." (PMID 27708385, 2016).
tumor (13 papers, 2012 to 2024). "Immune responses were enriched in tumours of the psyllium plus inulin group compared to psyllium plus RS, especially the pathways of humoral immunity, cytokines and their receptors, and interferon, along with Bst1 and Nfatc2 gene expression." (PMID 38745230, 2024). "Notably, individual cores from CT6 and CT7 exhibited enrichment for BST1 variants along with a second ORF (WDR69L341V), indicating an ability to identify multiple driver ORFs acting alone or in combination in a given tumour." (PMID 26806015, 2016).
cancer (11 papers, 2012 to 2025). A tumor composed of atypical neoplastic, often pleomorphic cells that invade other tissues. "While additional work is needed to validate these candidate oncogenes, including assessing variant activity compared with wild type, MAGEA6 and BST1 have both been previously implicated in cancer." (PMID 26806015, 2016). "For example, AGTR1, GRIN2A, ITPKB, and SLC8A3 were repressed by hypermethylation in six cancer types, and ADCY4, ADCY8, BST1, and PRKCB were inhibited by hypermethylation in five cancer types." (PMID 28060724, 2017). "First identified over 30 years ago as Mo5 myeloid differentiation antigen and 10 years later as Bone Marrow Stromal Cell Antigen 1 (BST-1), CD157 proved not to be restricted to the myeloid compartment and to have a diversified functional repertoire ranging from immunity to cancer and metabolism." (PMID 31817547, 2019).
infection (8 papers, 2016 to 2025). The state of being infected such as from the introduction of a foreign agent such as serum, vaccine, antigenic substance or organism. "The role of redox status and senescence in the development of RLS was further evaluated using the bst1 lesion mimic mutant which has lower H2O2 levels during pathogen infection." (PMID 29309539, 2018). "The PPI observed that the hub genes with the largest number of associated nodes in the weighted network played a crucial role in the immune cell recruitment and activation after infection, such CXCR1, VNN2, BST1, CREM, IL1R1, and CD48." (PMID 39692191, 2025). "Herein we describe our identification of BST1, an inositol deacylase of GPI-Aps in Candida albicans, was critical for GPI-APs cell wall attachment and host infection." (PMID 27708385, 2016). "Exceptions to this trend include the potential PLP substrates, 2/3 of which begin to show increased abundance at 12 h post-infection, with BST1 appearing to peak at 12 h rather than 24 h, indicating a potential temporal regulation of the two viral proteases." (PMID 34548480, 2021).
brain disorder (3 papers, 2015 to 2020). A disease affecting the brain or part of the brain. "It is unknown, however, whether variation of the CD157/BST1 gene is associated with other brain disorders." (PMID 26010484, 2015).
neurological diseases (3 papers, 2019 to 2025). "The BST1 gene encodes a molecule that facilitates pre-B-cell growth, and it has been involved in autoimmune and neurological diseases in humans." (PMID 40342962, 2025).
neurodegenerative disease (2 papers, 2024 to 2025). A disorder of the central nervous system characterized by gradual and progressive loss of neural tissue and neurologic function. "Additionally, we identified increase in BST1, a risk factor for neurodegenerative diseases (NDs)." (PMID 38470479, 2024).
kidney diseases (1 paper, 2022). "Although Bst1 is a cell-surface molecule that has a wide variety of functions through its varied enzymatic activities and downstream intracellular signaling pathways, no studies on the role of Bst1 in kidney diseases have been reported previously." (PMID 36267620, 2022).
BST1 also shares sentences with these, for which no sentence is quoted: leukemia (7 papers); malignant mesothelioma (4); psychiatric disorder (4); Alzheimer disease (3); brain ischemia (3); mesothelioma (3); paroxysmal nocturnal hemoglobinuria (3); REM sleep behavior disorder (3); autism (2); restless leg syndrome (2); schizophrenia (2); tuberculosis (2); acute lymphoblastic leukemia (1); acute promyelocytic leukemia (1); breast carcinoma (1); cardiovascular disease (1); Cerebral ischemia (1); COVID-19 (1); diabetes (1); glomerulosclerosis (1); hematologic malignancies (1); hemoglobinuria (1); Hodgkins lymphoma (1); immune dysfunction (1); kidney cancer (1); language disorder (1); late-onset Parkinson disease (1); liver cancer (1); lymph node metastasis (1); melanoma (1).
A further 16 diseases each share a sentence with BST1 in 1 paper.